INS (insulin)
Diseases named in the same sentence as INS in open-access papers (continued):
Sharing a sentence is not in itself a finding about the gene and the disease.
Insulin resistance (continued). "Insulin resistance is a major feature of type-2 diabetes, and it is manifested in the decreased response of insulin signaling pathway to insulin, which leads to the decreased glucose uptake in insulin-sensitive organs, such as skeletal muscle, fat and liver." (PMID 35806430, 2022). "However, while Hi-F diet mice developed glucose intolerance as well as liver and muscle insulin resistance (assessed via euglycaemic/hyperinsulinaemic clamp), obese Hi-ST mice maintained glucose tolerance and insulin action similar to lean, chow-fed controls." (PMID 36394259, 2022). "Conversely, in females, pathological conditions that determine an excess of androgens, such as polycystic ovary syndrome (PCOS), impaired hepatic glucose metabolism by decreasing insulin-stimulated glucose uptake and glycogen synthesis, thus predisposing PCOS females to insulin resistance." (PMID 35806934, 2022). "Thus, resistin induces insulin resistance and impairs insulin secretion in pancreatic beta cells via the increased expression of suppressor of cytokine signaling 3 (SOCS-3) and reduced AKT phosphorylation." (PMID 35634505, 2022). "Soy diets containing 35% animal protein, 35% soy protein, and 30% other plant protein consumed by GDM women for 6 weeks significantly reduced fasting plasma glucose, insulin resistance, and TG and increased insulin sensitivity and antioxidant effects in GDM women." (PMID 36558427, 2022). "Third, fat distribution is strongly associated with insulin resistance, but the UK Biobank cohort did not provide fasting samples so direct measures of insulin and inferred indices of insulin sensitivity are not available." (PMID 34875679, 2022). "Interestingly, all studies addressing the impact of EGCG on carbohydrate metabolism reported significant decreases in glucose and insulin levels, as well as insulin resistance (IR), with EGCG treatment." (PMID 35323719, 2022). "Hyperinsulinemia is commonly viewed as a compensatory response to insulin resistance, yet studies have demonstrated that chronically elevated insulin may also drive insulin resistance." (PMID 34921686, 2022). "Indeed, obesity is associated with a plethora of metabolic consequences such as hyperglycemia, insulin resistance and dyslipidemia, while it has recently been shown that the CP is a site of insulin secretion." (PMID 36313760, 2022). "Moreover, insulin resistance with dysregulated insulin signaling can activate the PI3K/Akt/mTOR and Ras/Raf/MAPK pathways." (PMID 35276833, 2022). "The association between insulin resistance and HGF levels was supported by two additional prospective studies, suggesting that insulin and HGF resistance might converge." (PMID 35269415, 2022). "Recent research shows that AD shares many common links with diseases related to insulin resistance, such as neuroinflammation, insulin signaling disorder, oxidative stress, advanced glycosylation end products (AGEs), mitochondrial dysfunction, and metabolic syndrome." (PMID 35563031, 2022). "Meanwhile, skeletal muscle is a major site of glucose metabolism by insulin, and the insulin resistance accompanying atherosclerosis might link to a decrease in muscle mass." (PMID 35559338, 2022). "In recent years, more studies have observed that patients with Prader–Willi syndrome have lower insulin levels and lower insulin resistance than body mass index-matched controls, which may suggest protected glucose metabolism." (PMID 35525976, 2022). "This disturbed endoplasmic reticulum environment induces islets β‐cell impairment and insulin resistance or production insufficient, leading to the efficiency of insulin‐mediated glucose uptake and utilization reduction and glucose regulation disorders in the liver." (PMID 35844917, 2022). "Importantly, Cyp7a1 is regulated by glucose‐ and insulin‐specific mechanisms and becomes dysregulated with diet‐induced obesity and/or insulin resistance." (PMID 35923133, 2022).
Insulin resistance (continued). "In addition to this, obesity leads to high levels of leptin, which acts as a cause for the release of pro-inflammatory cytokines and an exaggerated release of insulin leading to insulin resistance." (PMID 36355134, 2022). "This could be due to a decreased responsiveness of the target tissues of the animals in this group to insulin action (insulin resistance)." (PMID 36434695, 2022). "Further, various studies have assessed the toxic properties of accumulated kynurenine derivatives that, binded with insulin to form excitotoxic complexes, may lead to systemic disorders, including insulin resistance, blood presure changed, and renal damage." (PMID 36335368, 2022). "Upon obesity and insulin resistance, the compensated insulin secretion might accelerate the timing of puberty." (PMID 36465655, 2022). "One known determinant of insulin sensitivity/insulin resistance, which might further support our findings, are steroid hormones." (PMID 36431238, 2022). "In our results, the increase of insulin AUC, triglycerides and VLDL for the baseline–end intragroup analysis for placebo group patients are expected changes since insulin resistance is directly associated to insulin secretion as well as to triglycerides and VLDL concentrations." (PMID 36233611, 2022). "However, chronic hyperinsulinemia, which is present in insulin resistant mothers and corresponds to high insulin levels in the fetus, can induce insulin resistance in the fetus." (PMID 36619540, 2022). "Moreover, patrilineal female mice, as well as matrilineal female and male mice, showed increased serum insulin levels and insulin resistance, which is consistent with previous reports that BPA or HFD exposure can cause insulin resistance." (PMID 35281091, 2022). "MCP-1 has been associated with skeletal muscle inflammatory markers during insulin resistance, as it was found that the muscle-specific overexpression of MCP-1 in transgenic mice induced the local recruitment of macrophages and altered local insulin sensitivity." (PMID 36552772, 2022). "Moreover, several studies reported that 17β‐estradiol (E2)‐replete female rodents were protected against HFD‐induced insulin resistance, although insulin‐mediated glucose disposal was consistently reduced by 40–50% in male mice after HFD feeding." (PMID 35238495, 2022). "However, in non-diabetic subjects, the HOMA-IR is less useful and fasting insulin levels are an acceptable surrogate for insulin resistance." (PMID 35669689, 2022). "Mouse models showed that physiological reductions of PGC‐1α disrupt insulin signalling in liver, and mice with low hepatic PGC‐1α are more susceptible to hepatic steatosis, hypertriglyceridaemia, and oxidative liver damage – hallmarks of insulin resistance." (PMID 36101976, 2022). "In the non-pregnant state, insulin resistance has been linked to endothelial dysfunction and insulin-sensitizing interventions such as exercise and metformin have been shown to improve endothelial function." (PMID 35258482, 2022). "However, in clinical studies, the correlation between osteocalcin and insulin secretion or insulin resistance was still controversial." (PMID 36601005, 2022). "Adsorption of insulin to the line can mimic pseudo-insulin resistance of a newborn." (PMID 36542240, 2022). "InsR sensitizers can bind to the InsR to activate the insulin pathway independent of insulin; thus, InsR sensitizers have the potential to alleviate insulin resistance and minimize the risk of hypoglycemia." (PMID 35502441, 2022). "The severity of insulin resistance in adipose tissue may even proceed skeletal muscle, emphasizing the importance of identifying insulin sensitive mechanisms in adipose tissue." (PMID 36093068, 2022). "The HOMA-IR value for NPD was within the insulin-sensitive range (< 1.0) while the DIPD group had a significantly (p=< 0.0001) higher HOMA-IR value compared to the NPD which was in the range of significant insulin resistance (>2.9)." (PMID 35898447, 2022).
Insulin resistance (continued). "Another explanation of our findings could be connected with the insulin resistance presented in obesity and the stimulating effect of insulin on type 2 deiodinase activity, as shown in rat brown adipocytes." (PMID 35456211, 2022). "The insulin resistance of T2DM exerts increased circulating insulin and may increase osteoblast activity and bone formation." (PMID 36313749, 2022). "Altogether, Aβ peptides contribute to the development of central insulin resistance; accordingly, the neuroprotective effects of insulin might be reduced in the AD brain as a consequence of both insulin expression and function being downregulated." (PMID 35615716, 2022). "Another possible link between fetuin-A and insulin resistance is fetuin-A-stimulated inflammation in pancreatic adipocytes and islets, and fetuin-A-mediated c-Jun N-terminal kinase- and Ca-dependent impairment of insulin secretion." (PMID 34998417, 2022). "In summary, after blocking microbial vertical transmission by C-section, insulin resistance was ameliorated and insulin secretion was promoted in the offspring of mice with HFD-induced impairment of glucose metabolism, and these changes were accompanied by changes in faecal metabolite levels." (PMID 35941695, 2022). "It lowered the serum insulin levels and insulin resistance scores (HOMA-IR)." (PMID 35565712, 2022). "COVID-19 disease may cause prolonged uncontrolled elevated blood glucose level due to COVID-19-induced insulin resistance and COVID-19-impaired insulin production." (PMID 35888766, 2022). "The long-term effects of intranasal insulin remain unclear, and whether chronic administration may promote brain insulin resistance and worsen symptoms remains to be determined." (PMID 36555450, 2022). "Furthermore, OGTT revealed that MetS animals showed prominent insulin resistance, and their serum insulin levels were high compared to control animals." (PMID 35379188, 2022). "It develops when insulin resistance, which is physiologically increased during the second half of pregnancy and which is necessary to facilitate sufficient nutrient flux to the fetus, cannot be met by adequate insulin secretion." (PMID 36558379, 2022). "Interestingly, while low levels of circulating insulin are detected in insulin resistance due to dyslipidaemia, the present investigation found a strong negative connection between C peptide and total cholesterol and LDL." (PMID 36128550, 2022). "Fasting plasma glucose, insulin, and peripheral insulin resistance as assessed by HOMA-IR showed lower values in the evening as compared to the morning (ANOVA ‘time-of-day’, all p < 0.0001), but were not different across meals (ANOVA ‘time-of-day x condition’, all p = 0.415)." (PMID 35276920, 2022). "Moreover, PAK1 enrichment in GLUT4-myc-L6 myoblasts preserves normal insulin-stimulated GLUT4 translocation under insulin resistance conditions." (PMID 35222279, 2022). "Cellular insulin resistance is considered an impaired signaling response to insulin." (PMID 35741464, 2022). "- Lower levels among women with GDM in women with and without PCOS.- Inverse association with fasting insulin and insulin resistance." (PMID 36733795, 2022). "Unexpectedly, there were no significant changes of metabolites in the tryptophan-kynurenine pathway in the subgroup of PCOS with insulin resistance in comparison to patients with normal insulin sensitivity, as well as in the subgroups of PCOS with and without metabolic syndrome." (PMID 35721725, 2022). "There is sufficient evidence that HFD could lead to systemic insulin resistance, including suppression of insulin signaling in the hippocampus." (PMID 36364766, 2022). "However, obesity promotes insulin resistance and increases serum insulin levels, and high insulin levels increase leptin levels, eventually leading to leptin resistance in the nervous system and adipose tissue." (PMID 36557203, 2022).
Insulin resistance (continued). "Type 2 diabetes is associated with insulin resistance, impaired pancreatic β-cell insulin secretion, and nonalcoholic fatty liver disease." (PMID 35145074, 2022). "Insulin resistance refers to the decline in the efficiency of insulin in promoting glucose uptake and utilization and the compensatory secretion of excessive insulin by the body to produce hyperinsulinemia, which is the main cause and pathological phenomenon of T2DM." (PMID 36430365, 2022). "Decreased tissue response to normal insulin action is known as insulin resistance." (PMID 35655590, 2022). "It has been controversial whether the main factor of glucose intolerance is impaired insulin secretion or increased insulin resistance, and a definite mechanism remains to be further explored." (PMID 36569401, 2022). "The main reason for the rise in insulin levels in the control group could be the pancreas secreting and releasing more insulin to cope with rising glucose levels due to insulin resistance that developed concurrently with obesity." (PMID 35964948, 2022). "On the other hand, increased WC indicates the accumulation of abdominal fat and further affects insulin metabolism by releasing free fatty acids, which may lead to insulin resistance in muscle and liver and impair β-cell function." (PMID 35257014, 2022). "Insulin resistance in skeletal muscle has been attributed to several pathological conditions such as mitochondrial dysfunction, impaired glycogen synthesis and the accumulation of diacylglycerol, with subsequent impairment of insulin signaling." (PMID 35205333, 2022). "Contributing factors of the pathogenesis is the combination of insulin resistance, in which target tissues lose the capacity of properly responding to insulin, and the dysfunction of pancreatic β-cells, which secrete suboptimal levels of insulin." (PMID 35310942, 2022). "However, reducing Tti2 expression by half led to a reduction of the number of new neurons in the DG, a concomitant lowering of serum glucose and insulin concentrations, and to hallmarks of insulin resistance in skeletal muscles." (PMID 35377872, 2022). "Additionally, leflunomide treatment normalized blood glucose levels and overcame insulin resistance in glucose and insulin tolerance tests performed in ob/ob and high-fat diet (HFD)-fed mice." (PMID 35629988, 2022). "The central role of insulin resistance as a mediator of much of the metabolic burden of obesity, provides a rationale for exploring novel therapeutic strategies for obesity management (including those that target the insulin pathway)." (PMID 35889827, 2022). "FFAs also stimulate pancreatic insulin release and could thereby contribute to the insulin resistance we observed in our study." (PMID 36034417, 2022). "Insulin resistance and reduced insulin production are both key aspects of T2DM pathogenesis." (PMID 35600869, 2022). "In the case of functional tumors, where hormonal hypersecretion of counterregulatory hormones induces insulin resistance, treatment with insulin sensitizers such as metformin and pioglitazone may be preferred." (PMID 36422243, 2022). "Homa-IR is a method of estimating insulin resistance from fasting glucose and insulin levels." (PMID 36148302, 2022). "These events result in elevated insulin and fasting glucose levels and decreased glucose tolerance, which may indicate that insulin resistance is developing." (PMID 35806019, 2022). "Since obesity and insulin resistance are major contributors to complications in PCOS patients, anti-diabetic agents may effectively promote insulin action, thereby promoting weight loss and improving T2DM3." (PMID 36518222, 2022). "Studies have postulated that there is a paradoxical dual action of insulin that might contribute to selective hepatic insulin resistance (selective HIR) by modulating the hepatic lipid and glucose metabolism." (PMID 36479211, 2022).
Insulin resistance (continued). "Insulin resistance was assessed by the oral glucose insulin sensitivity (OGIS) index—deduced from a change in plasma concentrations of glucose and insulin during an oral glucose tolerance test (OGTT) and correlating strongly with the reference hyperinsulinemic-euglycemic clamp method." (PMID 35269594, 2022). "We tested among the numerous potential abnormalities that account for or contribute to muscle insulin resistance, the possibility that sustained elevated levels [Ca2+]i could make these cells resistant to insulin, a specific feature of T2D." (PMID 35547584, 2022). "Taken together, obtained results showed that postnatal overfeeding predisposes development of PCOS systemic insulin resistance, most likely as a result of worsened metabolic function of SAT, while VAT preserved its tissue insulin sensitivity through increased activity of AMPK." (PMID 36012206, 2022). "Previous study has confirmed that IRI > 2.5 is an important marker of insulin resistance, and insulin insensitivity means that the body's ability to regulate blood glucose is weakened, and the harm caused by hyperglycemia is more serious, and the incidence of nonrelapse increases significantly." (PMID 35340412, 2022). "In a study of serum metabolites based on non-diabetic middle-aged people, serum tryptophan and tyrosine concentrations are found to be related to glucose intolerance and insulin resistance, and these two amino acids are also higher in patients with diabetics with decreased insulin secretion." (PMID 35592630, 2022). "The mechanism of hyperglycemia is likely multifactorial and may involve induction of peripheral insulin resistance, decreased pancreatic insulin production, and other biochemical pathways." (PMID 39036518, 2022). "Furthermore, compensatory hyperinsulinemia occurs in insulin resistance, and there is a positive relationship between the circulating concentrations of insulin and myostatin, which promotes muscle atrophy." (PMID 36439272, 2022). "We monitored blood glucose and insulin throughout the HFD feeding regimen to determine whether HFD exacerbated insulin resistance in GIRKO mice." (PMID 34801552, 2022). "If the observed IR puncta defects are common features of insulin-resistant cells, then cells treated with other conditions expected to induce insulin resistance, such as chronic inflammation and high-nutrient levels, should exhibit IR puncta defects that phenocopy those caused by hyperinsulinemia." (PMID 36473871, 2022). "A clinical study conducted in Korean women found that increased serum glucose, insulin levels, and a higher HOMA-IR were associated with the multifocality of PTC, which suggested the correlation of hyperinsulinemia and/or insulin resistance and the aggressiveness of PTC." (PMID 35299970, 2022). "So far, it has not been clearly established whether all ceramides adversely affect the functioning of the insulin pathway, or whether there are certain ceramide species that play a pivotal role in the induction of insulin resistance." (PMID 35053322, 2022). "Disposition index (DI)—the product of AIRg and Si—is an indirect marker of whether the level of insulin secretion is appropriate for the level of insulin resistance; therefore, DI provides an integrative assessment of early phase β-cell responses." (PMID 35834023, 2022). "Inflammation in the skeletal muscle has been reported to increase muscle insulin resistance, suggesting that the reduction in muscle insulin resistance may have enhanced amino acid absorption into skeletal muscle." (PMID 35334814, 2022). "Our results suggest that in SAS patients, the upregulation of IL‐8, ON, and MN may induce a pro‐inflammatory phenotype in muscle tissue, leading to the development of insulin resistance and decreased insulin sensitivity." (PMID 36457269, 2022). "Moreover, insulin resistance dampens the inhibitory effect of insulin on FOXO1 and leads to persistent nuclear FOXO1 activity." (PMID 35868560, 2022).